FIGLA (folliculogenesis specific bHLH transcription factor)
Description:
Germline specific transcription factor implicated in postnatal oocyte-specific gene expression. Plays a key regulatory role in the expression of multiple oocyte-specific genes, including those that initiate folliculogenesis and those that encode the zona pellucida (ZP1, ZP2 and ZP3) required for fertilization and early embryonic survival. Essential for oocytes to survive and form primordial follicles. The persistence of FIGLA in adult females suggests that it may regulate additional pathways that are essential for normal ovarian development. Binds to the E-box (5'-CANNTG-3') of the ZPs (ZP1, ZP2, ZP3) promoters.
Synonyms: FIGalpha; bHLHc8; POF6
Tractability: No criterion of Open Targets' tractability assessment is met for any kind of drug.
Gene: Protein-coding gene on chromosome 2 (70,777,310 to 70,790,643, reverse strand). Ensembl gene ENSG00000183733.
Subcellular location: Nucleus
Gene Ontology:
Molecular function: bHLH transcription factor binding; E-box binding; protein binding; sequence-specific double-stranded DNA binding; DNA-binding transcription factor activity, RNA polymerase II-specific; RNA polymerase II transcription regulatory region sequence-specific DNA binding; DNA-binding transcription activator activity, RNA polymerase II-specific; protein dimerization activity; RNA polymerase II cis-regulatory region sequence-specific DNA binding
Biological process: developmental process; oocyte development; regulation of transcription by RNA polymerase II; positive regulation of transcription by RNA polymerase II
Cellular component: transcription regulator complex; chromatin; nucleus
Genetic constraint (gnomAD): Loss-of-function variants: 10 observed, 13.25 expected, observed/expected ratio (o/e) 0.75, 90% interval 0.47 to 1.28. The upper end of that interval is the gene's LOEUF score, 1.28, which puts it in group 5 of 6, group 1 being the genes least tolerant of losing a copy. Missense variants: 238 observed, 222.7 expected, observed/expected ratio (o/e) 1.07, 90% interval 0.96 to 1.19. Synonymous variants: 114 observed, 92.81 expected, observed/expected ratio (o/e) 1.23, 90% interval 1.05 to 1.43.
Homologues: Orthologues: chimpanzee FIGLA (98% identical), macaque FIGLA (92% identical), rabbit FIGLA (73% identical), pig FIGLA (69% identical), guinea pig FIGLA (66% identical), dog FIGLA (61% identical), mouse Figla (59% identical), rat Figla (58% identical), tropical clawed frog figla (32% identical), zebrafish figla (26% identical), Caenorhabditis elegans hlh-8 (15% identical), Drosophila melanogaster twi (15% identical). Paralogues in human: PTF1A (20% identical), TCF15 (19% identical), TWIST2 (19% identical), SCX (19% identical), TWIST1 (19% identical), TCF21 (18% identical), TCF24 (17% identical), MSC (16% identical), HAND2 (16% identical), TCF23 (16% identical), BHLHA9 (15% identical), HAND1 (15% identical), and 1 more.
Diseases named in the same sentence as FIGLA in open-access papers:
FIGLA is named in the same sentence as 9 diseases in open-access papers, as found by Europe PMC text mining. Sharing a sentence is not in itself a finding about the gene and the disease. The quoted sentences say what the papers report.
premature ovarian failure (3 papers, 2018 to 2025). "Here, we report a homozygous FIGLA variant identified in two Japanese sisters with non‐syndromic primary ovarian insufficiency (POI), and review the previously reported autosomal‐dominant and autosomal‐recessive FIGLA variants." (PMID 39896098, 2025). "Consistent with this, FIGLA variants have been identified in females with non‐syndromic primary ovarian insufficiency (POI) in both autosomal‐dominant and autosomal‐recessive forms." (PMID 39896098, 2025). "A previous study found that FIGLA haploinsufficiency may be associated with premature ovarian failure." (PMID 29914564, 2018).
cyst (2 papers, 2016 to 2023). A sac-like closed membranous structure that may be empty or contain fluid or amorphous material. "A number of transcription factors are known to play crucial roles in these processes as well as in germ cell cyst breakdown including Factor in the Germline Alpha (FIGLα) and Newborn Ovary Homeobox Gene (NOBOX)." (PMID 27341508, 2016).
Primary amenorrhea (2 papers, 2020 to 2021). "This variant was also described in patients with primary amenorrhea, together with another mutation in the REC8 and FIGLA genes." (PMID 32155011, 2020).
Infertility (1 paper, 2021). "Previous studies have shown that mutation and abnormal expression of the human FIGLA gene can cause developmental disorders in female germ cells, affecting primary follicle recruitment, and leading to secondary amenorrhea, infertility, POI, and other disorders." (PMID 34778283, 2021). "Together, these results indicate that FIGLA mutations affect the regulation and normal transcription of ZP genes, which may disrupt the normal formation of the zona pellicuda, cause disorders of oocyte maturation, and lead to POI and infertility." (PMID 34778283, 2021).
ovarian dysfunction (1 paper, 2021). The inability of the ovaries to function. "FIGLA can mediate ZP transcription under normal circumstances, but mutations may affect their transcriptional activity, resulting in ovarian dysfunction." (PMID 34778283, 2021). "Mutation of FIGLA may affect the transcription of zona pellucida genes and cause ovarian dysfunction." (PMID 34778283, 2021).
FIGLA also shares sentences with these, for which no sentence is quoted: cancer (1 paper); ovarian tumors (1); Sézary syndrome (1); steatosis (1).